IFNW1 (interferon omega 1)
Tractability: Small molecule: it has a binding pocket of medium quality. Antibody: UniProt places it where antibodies can reach, with medium confidence; UniProt predicts a signal peptide or a membrane-spanning region; its Gene Ontology location is reachable by antibodies, with medium confidence.
Gene: Protein-coding gene on chromosome 9 (21,140,632 to 21,141,832, reverse strand). Ensembl gene ENSG00000177047.
Subcellular location: Secreted
Gene Ontology:
Molecular function: protein binding; cytokine activity; cytokine receptor binding; type I interferon receptor binding
Biological process: adaptive immune response; B cell activation involved in immune response; cellular response to virus; humoral immune response; natural killer cell activation involved in immune response; regulation of cell cycle; response to exogenous dsRNA; response to virus; T cell activation involved in immune response; type I interferon-mediated signaling pathway; defense response
Cellular component: receptor complex; extracellular region
Genetic constraint (gnomAD): Loss-of-function variants: 0 observed, 0.0819 expected, observed/expected ratio (o/e) 0, 90% interval 0 to 1.89. That is too few expected variants to judge how well the gene tolerates losing a copy. Missense variants: 286 observed, 232.79 expected, observed/expected ratio (o/e) 1.23, 90% interval 1.12 to 1.36. Synonymous variants: 99 observed, 88.48 expected, observed/expected ratio (o/e) 1.12, 90% interval 0.95 to 1.32.
Homologues: Orthologues: chimpanzee IFNW1 (99% identical), macaque IFNW1 (94% identical), rabbit IF1BB1 (68% identical), rabbit IF1BB2 (68% identical), rabbit IF1BB5 (68% identical), rabbit IF1BB6 (67% identical), rabbit IF1BB3 (66% identical), pig IFN-OMEGA-5 (65% identical), pig IFN-OMEGA-3 (64% identical), pig IFN-OMEGA-7 (63% identical), pig IFN-OMEGA-6 (62% identical), pig IFN-OMEGA-2 (49% identical), and 3 more. Paralogues in human: IFNA2 (59% identical), IFNA8 (57% identical), IFNA10 (57% identical), IFNA4 (56% identical), IFNA5 (56% identical), IFNA17 (56% identical), IFNA6 (56% identical), IFNA13 (55% identical), IFNA14 (55% identical), IFNA1 (55% identical), IFNA16 (55% identical), IFNA21 (55% identical), and 4 more.
Diseases named in the same sentence as IFNW1 in open-access papers:
IFNW1 is named in the same sentence as 14 diseases in open-access papers, as found by Europe PMC text mining. Sharing a sentence is not in itself a finding about the gene and the disease. The quoted sentences say what the papers report.
dermatomyositis (1 paper, 2019). Dermatomyositis (DM) is a type of idiopathic inflammatory myopathy characterized by evocative skin lesions and symmetrical proximal muscle weakness. "The MS-IFNB1 Z scores were higher than the PBMC-derived Z scores, but IFNW1, IFNA2, and IFNB1 were still highly significant (Z > 3) for all SLE WB, PBMC, and affected tissues, the control dermatomyositis dataset, but not the sepsis dataset." (PMID 31044165, 2019).
discoid lupus erythematosus (1 paper, 2019). A chronic, autoimmune skin condition that manifests with a red, scaling rash, most often found on the face, ears, and scalp; these lesions often lead to permanent scarring and dyspigmentation. "Discoid lupus erythematosus (DLE) was significantly separated from control skin by all of the signatures (p < .05); IFNB1 had the greatest size (Hedge’s g = 12.4) followed by IFNW1 (g = 9.7), IFNG (g = 8.7), IFNA2 (g = 7.9), IL12 (g = 5.2), and TNF (g = 2.8)." (PMID 31044165, 2019).
HIV-1 infection (1 paper, 2024). The type species of lentivirus and the etiologic agent of acquired immunodeficiency syndrome (AIDS). "Therefore, an investigation of whether the association of gene level variation in IFNW1 with HIV VL is true shall preferably be in a cohort of participants similarly at an early stage of HIV-1 infection and including participants of African descent." (PMID 38698440, 2024).
melanoma (1 paper, 2012). A malignant, usually aggressive tumor composed of atypical, neoplastic melanocytes. "In this study we observed that, of all the type I IFN variants evaluated, two linked polymorphisms rs10964862 and rs10964859, located at 3′UTR of IFNW1, were associated with detrimental effects on survival of melanoma patients." (PMID 23209811, 2012). "Based on our observations, we hypothesize that the region of 26 kb encompassing IFNW1 and IFNA21 could be a regulatory region in chromosome 9p22, containing natural genetic variants, which might play a role in disease outcome in melanoma." (PMID 23209811, 2012).
tumor (3 papers, 2016 to 2023). "In line with this, we found in the TCGA dataset that loss of expression of IFNA13, IFNA21, IFNA6, IFNA8, IFNB1, or IFNW1 was correlated to poor survival, increasing the evidence for the importance of the tumor-stroma microenvironment interaction in gliomagenesis." (PMID 27172220, 2016).
infection (2 papers, 2017 to 2024). The state of being infected such as from the introduction of a foreign agent such as serum, vaccine, antigenic substance or organism. "Across 19 type 1 IFN genes, only IFNW1 was associated with HIV-1 study entry VL in a cohort of ART-naïve individuals in early stages of their infection, however, this was no longer significant in sensitivity analyses that controlled for population structures using LME." (PMID 38698440, 2024).
IFNW1 also shares sentences with these, for which no sentence is quoted: COVID-19 (1 paper); endothelial dysfunction (1); infectious disease (1); lupus erythematosus (1); lupus nephritis (1); osteoarthritis (1); Sepsis (1); viral infection (1).